NUCKS1 (nuclear casein kinase and cyclin dependent kinase substrate 1)
Description:
Chromatin-associated protein involved in DNA repair by promoting homologous recombination (HR). Binds double-stranded DNA (dsDNA) and secondary DNA structures, such as D-loop structures, but with less affinity than RAD51AP1.
Synonyms: NUCKS; JC7
Tractability: PROTAC: ubiquitination databases record sites on it; its protein half-life has been measured.
Gene: Protein-coding gene on chromosome 1 (205,712,822 to 205,750,270, reverse strand). Ensembl gene ENSG00000069275.
Subcellular location: Nucleus; Chromosome
Subcellular location (Human Protein Atlas): Nucleoplasm; Nucleoli
Gene Ontology:
Molecular function: chromatin binding; DNA-binding transcription factor binding; double-stranded DNA binding; protein binding; RNA binding; transcription coactivator activity; single-stranded DNA binding
Biological process: cellular response to X-ray; double-strand break repair via homologous recombination; host-mediated activation of viral genome replication; host-mediated activation of viral transcription; host-mediated perturbation of viral genome replication; interstrand cross-link repair; regulation of DNA replication; regulation of DNA strand elongation; replication fork processing; chromatin organization; gene conversion; intracellular glucose homeostasis; positive regulation of transcription by RNA polymerase II; regulation of insulin receptor signaling pathway
Cellular component: chromatin; chromosome; cytoplasm; nucleolus; nucleoplasm; nucleus
Genetic constraint (gnomAD): Loss-of-function variants: 2 observed, 22.06 expected, observed/expected ratio (o/e) 0.0906, 90% interval 0.036 to 0.28. The upper end of that interval is the gene's LOEUF score, 0.28, which puts it in group 1 of 6, group 1 being the genes least tolerant of losing a copy. Missense variants: 165 observed, 250.33 expected, observed/expected ratio (o/e) 0.66, 90% interval 0.58 to 0.75. Synonymous variants: 87 observed, 90.35 expected, observed/expected ratio (o/e) 0.96, 90% interval 0.81 to 1.15.
Homologues: Orthologues: chimpanzee NUCKS1 (100% identical), macaque NUCKS1 (98% identical), guinea pig NUCKS1 (97% identical), rabbit NUCKS1 (95% identical), pig NUCKS1 (93% identical), rat Nucks1 (93% identical), rat LOC120093168 (93% identical), mouse Nucks1 (92% identical), dog NUCKS1 (81% identical), zebrafish nucks1a (62% identical), zebrafish nucks1b (47% identical). Paralogues in human: RAD51AP1 (33% identical).
Diseases named in the same sentence as NUCKS1 in open-access papers:
NUCKS1 is named in the same sentence as 63 diseases in open-access papers, as found by Europe PMC text mining. Sharing a sentence is not in itself a finding about the gene and the disease. The quoted sentences say what the papers report.
breast carcinoma (11 papers, 2009 to 2025). "With regard to the well-known breast cancer markers, an association between NUCKS1 immunoexpression and CK 5/6 and Ki-67 was observed." (PMID 25187794, 2014). "Importantly, these miRNAs target genes associated with metastasis as NUCKS1, mainly in non-small cell lung and breast cancer, and androgen response, G3BP1, suggesting their potential role in suppressing the progression of tumors and enhancing therapy sensitivity." (PMID 40004509, 2025). "miR-641 is expressed at a low level and NUCKS1 shows a high level in breast cancer cells (Hs-578T, MCF7, HCC1937, and MAD-MB-231)." (PMID 36835100, 2023). "miR-199a-5p enhanced radiosensitivity in breast cancer cells, and its radiation target NUCKS1 was identified." (PMID 37569824, 2023). "NUCKS1 phosphorylation at various phosphosites is also known to correlate with breast cancer resistance to retinoic acid, known to exert anti-proliferative effects in several breast cancer cell lines." (PMID 36661191, 2023). "Studies on lung cancer, breast cancer and gastric cancer have shown that NUCKS1 functions through the PI3K signaling pathway." (PMID 37582772, 2023). "In breast carcinoma, NUCKS1 exhibited higher expression than other investigated markers (including Ki67, estrogen receptor, progesterone receptor, human epidermal growth factor receptor 2, and cytokeratin 5/6)." (PMID 35069784, 2022). "Consistently, transwell assay revealed that NUCKS1 overexpression partially blocked the antimigration and anti-invasion effects of miR-641 on the breast cancer in vitro." (PMID 35069784, 2022). "To further identify the mediatory role of NUCKS1 in linking the effect of miR-641 on the breast cancer progression, we overexpressed the NUCKS1 in both MDA-MB-231 and MCF7 cells." (PMID 35069784, 2022). "The upregulation of miR-641 inhibited NUCKS1 expression at both mRNA and protein levels in breast cancer cells." (PMID 35069784, 2022). "miR-641 functioned as a tumor suppressor through the PI3K/AKT signaling pathway via targeting NUCKS1 in breast cancer." (PMID 35069784, 2022). "The expression levels of miR-641 were downregulated, while the expression levels of nuclear casein kinase and cyclin-dependent kinase substrate 1 (NUCKS1) were increased in breast cancer cell lines." (PMID 35069784, 2022). "By using real-time PCR and western blotting assays, we assessed the NUCKS1 expression in breast cancer cell lines (Hs-578T, MCF7, HCC1937, and MAD-MB-231)." (PMID 35069784, 2022). "In breast carcinoma, NUCKS1 has exhibited higher expression than other investigated markers (including Ki67, estrogen receptor, progesterone receptor, human epidermal growth factor receptor 2, and cytokeratin 5/6)." (PMID 29619377, 2018). "Albeit there are little functional cancer-related data on NUCKS1, several studies suggest that there are some links, particularly between NUCKS1/NUCKS1 expression and breast cancer." (PMID 27542204, 2016). "The presence of NUCKS1 in rapidly growing cells, including breast cancer cells, was previously confirmed using a variety of biochemical and immunochemical methods." (PMID 25187794, 2014). "We also found that NUCKS1 was significantly upregulated in breast cancer cells, indicating that NUCKS1 might be an oncogene for breast cancer pathogenesis." (PMID 35069784, 2022). "Additionally, NUCKS1 is also highly expressed in breast cancer with obesity; these findings are consistent with results obtained in a previous study." (PMID 29619377, 2018). "However, the human NUCKS1 gene also belongs to a group of co-expressed genes located on chromosomal region 1q32.1 that is amplified in some breast cancers, and in other cancers." (PMID 27542204, 2016). "The aim of the present study was to establish whether NUCKS1 expression may be considered as a prognostic marker of breast carcinoma, and whether this marker correlates with other clinicopathological features." (PMID 25187794, 2014).
breast carcinoma (continued). "Additionally, NUCKS1 is also highly expressed in breast cancer with obesity." (PMID 35069784, 2022). "miR-383-3p and -5p enhanced the apoptosis and UV sensitivity of breast cancer cells, and their radiation targets CRYAB, CCND2, GATA3, NUCKS1, MAP3K20, and MDM2 were identified, while ATR is targeted by miR-383-5p." (PMID 37569824, 2023). "miR-641 inhibits breast cancer cell migration and enhances apoptosis, which is reversed by PI3K inhibitor, suggesting miR-641-induced apoptosis through the targeting of the NUCKS1/PI3K/AKT axis." (PMID 36835100, 2023). "In the present study, a routine immunohistochemical method was used to analyze the expression of ER, PR, CK 5/6, HER2 and Ki-67, as well as a novel hypothetical marker, NUCKS1, in 90 cases of invasive non-specific breast carcinoma." (PMID 25187794, 2014). "NUCKS1 is a critical regulator of PI3K/AKT signaling, which prompts us to determine whether dysregulation of miR-641 could alter the activity of PI3K/AKT signaling in breast cancer cells." (PMID 35069784, 2022).
gastric cancer (6 papers, 2020 to 2023). A primary or metastatic malignant neoplasm involving the stomach. "NUCKS1 promotes gastric cancer cell aggressiveness by regulating autophagy." (PMID 37528150, 2023). "Interestingly, NUCKS1 plays an oncogenic role in a number of cancers, including cervical squamous cell carcinoma, breast cancer, lung cancer, colorectal cancer, gastric cancer, and hepatocellular carcinoma." (PMID 37528150, 2023).
lung carcinoma (6 papers, 2016 to 2023). "By demonstrating that circATP9A fosters the progression of NSCLC through its interaction with the HuR protein and the subsequent amplification of NUCKS1 mRNA and protein levels, we have uncovered a novel regulatory mechanism in lung cancer pathology." (PMID 38049814, 2023). "In lung cancer, NUCKS1 promoted cell growth, migration, and invasion through the PI3K/Akt signaling pathway." (PMID 37528150, 2023). "Then, we determine the correlation between NUCKS1 levels and miR-137 expression levels in the same human lung cancer specimens." (PMID 26989074, 2016). "Spearman's rank correlation analysis showed that the expression levels of NUCKS1 and miR-137 in 50 human lung cancer specimens were inversely correlated (Spearman's correlation r = −0.6468)." (PMID 26989074, 2016). "In summary, we have identified a link between miR-137, NUCKS1 and chemoresistance that is a novel constituent of lung cancer tumorigenesis." (PMID 26989074, 2016). "Furthermore, we measured the levels of NUCKS1 proteins in human lung cancer specimens and normal tissues." (PMID 26989074, 2016). "However, the status of NUCKS1 expression in lung cancer remains unknown." (PMID 26989074, 2016).
Parkinson disease (6 papers, 2016 to 2025). A progressive degenerative disorder of the central nervous system characterized by loss of dopamine producing neurons in the substantia nigra and the presence of Lewy bodies in the substantia nigra and locus coeruleus. "Single nucleotide polymorphisms of NUCKS1 have been linked through genome wide association studies to Parkinson’s, a protein aggregation-related disease." (PMID 30858367, 2019). "Seven probes i.e. 226880_at,223661_at, 229353_s_at, 224582_s_at, 217802_s_at, 224581_s_at and222424_s_at were identified in the expression of NUCKS1 gene ingene expression profile of substantianigra of postmortem brainfrom Parkinson's disease patients." (PMID 31719764, 2019). "Simultaneously, evaluation ofexpression of other 17 genes with NUCKS1 revealed that three ofthem are also have different expression in Parkinson's cases i.e.RAB7L1, NFASC and MFSD4 at P<0.01 and multiple testingcorrection (MTC) threshold 0.000345." (PMID 31719764, 2019). "We found genes that are related to cancer (NBN, FAM84B), Huntington's disease (DCTN4), Parkinson's disease (NUCKS1), Alzheimer's disease (SMC3), amongst others." (PMID 27257970, 2016). "Specific common coding variants in SPNS1 and MLX may be involved in Parkinson’s disease, and burden tests of rare variants further support that CNIP3, LSM7, NUCKS1 and the polyol/inositol phosphate biosynthetic pathway are associated with the disease." (PMID 37804111, 2024). "The expression of NUCKS1 gene in Parkinson's disease has beenevaluated using GEO2R tool." (PMID 31719764, 2019). "Each probe represent differentregion of NUCKS1 gene and may have same or different transcript.All these probes are found to be deregulated in Parkinson's casescompared with healthy individuals." (PMID 31719764, 2019). "GWAS have identified NUCKS1 as one of five transcripts of the PARK16 locus on 1q32, which is a susceptibility locus associated with Parkinson disease (PD)." (PMID 29619377, 2018).
osteosarcoma (5 papers, 2021 to 2025). A usually aggressive malignant bone-forming mesenchymal neoplasm, predominantly affecting adolescents and young adults. "The IHC results indicated that NUCKS1 expression was positively associated with the stage of osteosarcoma." (PMID 37528150, 2023). "To dissect the underlying molecular mechanism whereby NUCKS1 promoted osteosarcoma cell tumorigenesis and metastasis, we used RNA-seq to identify the downstream genes of NUCKS1." (PMID 37528150, 2023). "NUCKS1, which is significantly increased in osteosarcoma, enhances asparagine synthesis by transcriptionally upregulating ASNS expression." (PMID 39090094, 2024). "Asparagine, but not glutamate, rescued the decrease in cell proliferation induced by NUCKS1 knockdown, suggesting that NUCKS1 promoted osteosarcoma cell growth in a manner dependent on asparagine synthesis." (PMID 37528150, 2023). "This study reports that NUCKS1 is increased in osteosarcoma tissue and promotes asparagine synthesis via transcriptional upregulation of ASNS expression." (PMID 37528150, 2023). "Then, we examined NUCKS1 expression in 70 formalin-fixed and paraffin-embedded osteosarcoma tissues and 11 normal bone tissues using immunohistochemical (IHC) staining." (PMID 37528150, 2023). "Consistent with an oncogenic role of NUCKS1 in osteosarcoma cells, elevated NUCKS1 expression promoted cell proliferation and migration, as indicated by an increase in the number of colonies and migrated cells." (PMID 37528150, 2023). "To further confirm the oncogenic role of NUCKS1 in osteosarcoma, we first investigated NUCKS1 expression in the TNMplot database." (PMID 37528150, 2023). "Collectively, these data indicate that NUCKS1 accelerated osteosarcoma cell growth and metastasis in vitro and in vivo." (PMID 37528150, 2023). "To better understand the role of NUCKS1 in osteosarcoma, we subsequently investigated the effects of NUCKS1 on tumorigenesis and metastasis in vivo." (PMID 37528150, 2023). "Taken together, these data strongly verify that ASNS is increased in osteosarcoma tissues and that the expression of ASNS was positively associated with NUCKS1." (PMID 37528150, 2023). "Consistently, our data showed that LINC00629 acted as a miR-4768-3p sponge and upregulated NUCKS1 expression in osteosarcoma." (PMID 37528150, 2023). "Taken together, our findings highlight the role of NUCKS1 in regulating asparagine metabolism and reveal that LINC00629 is an important regulator of NUCKS1 that contributes to NUCKS1 upregulation in osteosarcoma." (PMID 37528150, 2023). "Subsequently, we transfected miR-4768-3p, miR-592, and let-7f-1-3p into osteosarcoma cells, and the expression of NUCKS1 was detected by Western Blotting." (PMID 37528150, 2023). "To evaluate the contribution of NUCKS1 to the development of human osteosarcoma, we first knocked down NUCKS1 with two independent shRNAs in 143B and MNNG/HOS cells." (PMID 37528150, 2023). "Taken together, these findings indicate that NUCKS1 elevates asparagine synthesis and suppresses l-ASNase-induced osteosarcoma cell death." (PMID 37528150, 2023). "Collectively, these results suggest that NUCKS1 promotes osteosarcoma cell growth and metastasis partly in a manner dependent on ASNS." (PMID 37528150, 2023). "In this work, we found that NUCKS1 played an oncogenic role in osteosarcoma and promoted asparagine synthesis by upregulating ASNS expression." (PMID 37528150, 2023). "Collectively, our findings highlight the role of NUCKS1 in regulating asparagine metabolism and reveal that LINC00629 is an important regulator of NUCKS1 that contributes to NUCKS1 upregulation in osteosarcoma." (PMID 37528150, 2023). "Collectively, our data indicate that LINC00629 acts as a miR-4768-3p sponge and promotes NUCKS1 expression in osteosarcoma cells." (PMID 37528150, 2023). "Inhibition of ASNS or reduction of Asn decreased osteosarcoma cell aggressiveness and impaired the promoting effects of NUCKS1 on tumorigenesis and metastasis." (PMID 37528150, 2023).
osteosarcoma (continued). "Our findings suggested that ASNS was upregulated in osteosarcoma tissues with high NUCKS1 expression compared with those with low NUCKS1 expression." (PMID 37528150, 2023). "To determine whether NUCKS1 promotes osteosarcoma cell tumorigenesis and metastasis by upregulating ASNS, we first investigated the role of ASNS in osteosarcoma and knocked down ASNS with two independent shRNAs in 143B and MNNG/HOS cells." (PMID 37528150, 2023). "Depletion of NUCKS1 decreased osteosarcoma cell proliferation and metastasis in vivo and in vitro." (PMID 37528150, 2023). "However, the biological functions and regulatory mechanism of NUCKS1 in osteosarcoma have not been fully understood." (PMID 37528150, 2023). "To confirm it, we first detected NUCKS1 expression in LINC00629-depleted osteosarcoma cells." (PMID 37528150, 2023). "In this study, we reported that NUCKS1 was significantly increased in osteosarcoma." (PMID 37528150, 2023). "Overexpression of NUCKS1 accelerated osteosarcoma cell aggressiveness." (PMID 37528150, 2023). "We thus assessed the effects of NUCKS1 on the enzyme activities of ASNS in osteosarcoma cells." (PMID 37528150, 2023). "High expression of NUCKS1 also promotes osteosarcoma cell survival and tumor formation." (PMID 37528150, 2023). "Taken together, these data strongly indicate that NUCKS1 is a key oncogene in osteosarcoma." (PMID 37528150, 2023). "Similarly, our data uncovered the role of NUCKS1 in osteosarcoma and found that NUCKS1 facilitated osteosarcoma cell growth and metastasis." (PMID 37528150, 2023). "Subsequently, we found that LINC00629 elevated NUCKS1 in osteosarcoma." (PMID 37528150, 2023). "Compared with normal tissues, the expression of NUCKS1 was significantly increased in osteosarcoma." (PMID 37528150, 2023). "Furthermore, we explored the relationship between ASNS and NUCKS1 in osteosarcoma tissues." (PMID 37528150, 2023). "Mechanistically, NUCKS1 facilitated asparagine (Asn) synthesis by transcriptionally upregulating asparagine synthetase (ASNS) expression and elevating the levels of Asn in osteosarcoma cells, leading to increased cell growth and metastasis." (PMID 37528150, 2023). "Collectively, these results revel that LINC00629 promotes NUCKS1 and ASNS expression in osteosarcoma cells." (PMID 37528150, 2023). "To evaluate the clinical importance of the NUCKS1-ASNS axis and determine their correlation in osteosarcoma, we first investigated ASNS expression in the TNMplot database." (PMID 37528150, 2023). "Similarly, our findings reported that NUCKS1 was a new regulator of ASNS and identified ASNS as a downstream gene of NUCKS1 that promoted osteosarcoma cell growth and metastasis." (PMID 37528150, 2023). "Taken together, these findings indicate that NUCKS1 could bind the promoter of ASNS and upregulate ASNS expression in osteosarcoma cells." (PMID 37528150, 2023). "To uncover the molecular mechanism whereby LINC00629 upregulated NUCKS1, we first analyzed the mRNA levels of NUCKS1 in osteosarcoma cells with or without LINC00629 knockdown." (PMID 37528150, 2023). "Therefore, our results uncover a novel role of NUCKS1 in regulating asparagine metabolism and identify LINC00629 as an important regulator of NUCKS1 upregulation in osteosarcoma." (PMID 37528150, 2023). "Subsequently, we overexpressed NUCKS1 in osteosarcoma cells with or without ASNS knockdown." (PMID 37528150, 2023). "To further investigate whether LINC00629-upregulated ASNS expression via NUCKS1, we then knocked down NUCKS1 expression in osteosarcoma cells with or without LINC00629 overexpression." (PMID 37528150, 2023).
ovarian carcinoma (4 papers, 2014 to 2025). A malignant neoplasm originating from the surface ovarian epithelium. "In recent years, NUCKS1 has been found to play an important role in the development and progression of many types of female reproductive cancers, such as ovarian cancer and endometrial cancer cancer." (PMID 37582772, 2023). "Increased NUCKS1 expression has been reported in several cancers, including ovarian cancer." (PMID 26989074, 2016). "The abundance of NUCKS1 in rapidly growing cells, and the overexpression of NUCKS1 mRNA in ovarian cancer, supports this hypothesis." (PMID 25187794, 2014).